CD4 (CD4 molecule)
Diseases named in the same sentence as CD4 in open-access papers (continued):
Sharing a sentence is not in itself a finding about the gene and the disease.
viral infection (continued). "Since B cells, CD4+ T cells, and DCs are all known to regulate antibody responses, it is possible that an increased level of viral infection of one of these cell types during the acute phase was responsible for the antibody defect in Myd88-deficient mice." (PMID 19214214, 2009). "Central memory CD4+ T cells and naive cells were both involved in the viral infection/replication process despite the significantly lower SIV RNA levels in naive than in central memory cells." (PMID 19930655, 2009). "Although most HIV-1 infected patients and SIV infected animals make virus-specific CD4+ T cell responses, these responses are usually kept in check by ongoing virus infection." (PMID 19165322, 2009). "None of the siRNAs tested resulted in efficient HIV-1 reporter virus infection of quiescent CD4+ T-cells." (PMID 19300495, 2009). "While the frequency of infected pDC was relatively modest at 4% it was similar to that of CD4+ T cells, the principle cells infected in lymph nodes at this time, suggesting that pDC are a significant target of virus infection." (PMID 19424421, 2009). "Adaptive immunity includes humoral components (antibodies produced by B cells) and, especially important in viral infections, cellular immune responses (CD4+ and CD8+ T cells)." (PMID 21994541, 2009). "The helper activities of antigen-specific CD4+ T cells have been shown to mediate the control of many viral infections and are critical in maintaining HIV-1 suppression." (PMID 19165342, 2009). "We show here that CVB3-specific CD4+ T cells display an effector phenotype and a Th1 cytokine profile, and are enriched among CD4+ T cells in peripheral sites of virus infection that are major targets of CVB3 pathogenesis." (PMID 19834548, 2009). "As expected, CD4+ T-cells stimulated with PHA/IL-2 were highly susceptible to infection by the HSA reporter virus and the virus infection was strongly diminished in the presence of AZT." (PMID 19300495, 2009). "Following virus infection, a mild inflammatory infiltration of the lungs by lymphocytes and neutrophils occurred, with activated CD4+ and CD8+ T cell subsets being both recruited to the airways." (PMID 18335041, 2008). "In chronic viral infections, phenotypic and functional heterogeneity of memory CD4 T cells responses is believed to be regulated by antigen persistence and high/low levels of antigen load." (PMID 18974880, 2008). "The active contribution of LFA-1/ICAM-1 interaction to HIV spread has been described during free virus infection of CD4 T cells and infection mediated by DC." (PMID 18377648, 2008). "Only HIV-1 infected CD8+ and CD4+ T-cells, showed that viral infection was productive as both T-cell populations showed a HIV-1 gag-specific band when RT-PCR analysis was performed." (PMID 18923697, 2008). "Together, these results suggest that CD4+ T cells from coinfected animals are more permissive to viral infection and replication, leading to more rapid destruction of memory T cells." (PMID 18648516, 2008). "What are the evolutionary benefits of a delay in antiviral T cell division, given that CD8+ and CD4+ T cells are essential for eliminating most virus infections and for driving other immune responses?" (PMID 18404208, 2008). "That CD4+ T-cell help is central to adaptive immunity is well established, but few antigen-specific systems have been developed to dissect the role of CD4+ T cells in a viral infection." (PMID 16494717, 2006). "This chronic viral infection diminishes the immune system by attacking CD4 cells." (PMID 42044105, 2026). "Thus, eliciting a strong CD4-CTL response has been considered an important goal of vaccination against several viral infections." (PMID 41499515, 2026).
viral infection (continued). "Viral infections are known to activate CD4+ and CD8+ T-cells in the body." (PMID 40125151, 2025). "The role of CD4 T cells in the control of viral infections beyond their traditional helper activity has been increasingly recognized, and CD4 T cells with cytotoxic capacity have been reported for the nearly ubiquitous betaherpesviruses HCMV (human cytomegalovirus) and HHV-6B (human herpesvirus 6B)." (PMID 41376632, 2025). "Given that the formal requirement for CD4+ T cell help to generate immune responses varies across viral infections and vaccines, we sought to determine the role of CD4+ T cells in the context of cellular and humoral responses to nucleoside‐modified mRNA and Ad‐vectored vaccines against SARS‐CoV‐2." (PMID 39604225, 2025). "However, during viral infections, B cells recognizing virion epitopes endocytose and process virions for antigen presentation to CD4+ helper T (Th) cells specific for virion proteins." (PMID 40181970, 2025). "Moreover, we demonstrate that p13 expression affects macrophage polarization to favor the recruitment of CD4+ T cells, the primary target of the virus, potentially facilitating the spread of viral infection and the development of disease." (PMID 40284913, 2025). "Chronic antigen exposure drives CD4+ T cell senescence, yet how autoimmunity and persistent viral infections differentially shape T cell differentiation and function remains unclear." (PMID 41235706, 2025). "IL-2 is chiefly synthesized via CD4+ T cellsafterwards antigen or mitogen stimulation and is also a cytokine with pleiotropiceffects, which takepart in the immune response and protection against viral infection." (PMID 40961276, 2025). "Importantly, the changes observed in the T-cell repertoire were accompanied by altered functional responses of CD8+ and CD4+ T cells in herpes virus-positive animals, which impaired their ability to clear the viral infection." (PMID 40732672, 2025). "CD4+ T cell memory plays an essential role in viral infections." (PMID 41034205, 2025). "Signs of increased immune signaling are present despite impaired SOCE and may be secondary to the patient’s persistent viral infection as it not only affected CD4+ Tem cells, but also CD8+ T cells and NK cells." (PMID 41200103, 2025). "Importantly, macrophages, exhibit a slower rate of viral infection compared to activated CD4+ T cells." (PMID 39623137, 2025). "While human and murine T cells do not have exactly the same glycocalyx profiles or glycan remodeling dynamics during ex vivo activation, the α2,6-linked sialic acid modification has been shown to also decline in all T cell subsets including CD8+, CD4+, and γδ T cells upon viral infections in humans." (PMID 41004592, 2025). "The data suggest that this significant shift in the immune response may lead to the recruitment of CD4+ T cells, the primary target of the virus, and potentially facilitate the spread of viral infection and the development of disease." (PMID 40284913, 2025). "While elevated CD95 expression in T cells is common following various viral infections, the role of CD95 in CD4+ T cells in early infection appears to be associated with activation, whereas increased expression of CD95 is associated with disease progression in HIV infection." (PMID 40092978, 2025). "Thus, these species-specific functional differences in CD4+CTLs during viral infections must be further explored in other pathologies, such as autoimmunity and cancers." (PMID 41009359, 2025). "Th1 polarized CD4 T cells express high levels of the transcription factor Tbet and are a major source of IFNγ during viral infection, a cytokine critical for activating innate and adaptive immunity to clear a virus infection." (PMID 38512979, 2024).
viral infection (continued). "Lymphopenia (70/μL; RV: 1400-4200*).Low CD4+ lymphocytes (13%; RV: 28.4-44.4***).Low serum IgG (252 mg/dL; RV: 639-1349**) IgA (37 mg/dL; RV: 70-312**) and IgM (24 mg/dL; RV: 56-352**).Reduced proliferation assays.Recurrent severe viral infections." (PMID 39944559, 2024). "CD4+ IL-17-producing cells, designated as Th17 cells, can enhance the Th1 response and aid in promoting cytotoxic T-cell activity during viral infections, and a similar increase in the frequency of IL-17-producing CD4+ T cells was identified in the splenocytes of mice vaccinated with CC-OMV-M2e." (PMID 39066362, 2024). "CD8+ and CD4+ T cells play a crucial role in clearing viral infections." (PMID 39881722, 2024). "Our goal was to generate antigen-specific memory CD4+ T cells by heterologous priming with protein immunization or viral infection that could provide help during a primary influenza response." (PMID 39283916, 2024). "Notably, the more potent antibodies, 3BNC117 and VRC01, maintained their ability to fully block the viral infection of CD4+ T cells, even in the presence of semen." (PMID 38501840, 2024). "Collectively, these studies suggest that naïve CD4+ T cell heterogeneity in mice and humans is dynamic in response to environmental type I IFN levels in viral infections and type I IFN–associated autoimmune diseases and suggest a role for type I IFN in regulating naïve T cells." (PMID 39321257, 2024). "Moreover, a strong capacity of CD8+ T cells ex vivo to suppress viral infection of autologous CD4+ T cells is a characteristic that we have consistently found in HIV-1 controllers and in HIV-2 controllers." (PMID 38212337, 2024). "T cell kinetics follow an expected pattern for acute viral infection, where Th1 cells continually increased through day 14 after infection consistent with previous reports that both CD4 and CD8 T cells are recruited to the brain following SINV infection and continually increase through 10 dpi." (PMID 38695564, 2024). "This indicates that viral infection indeed leads to a decrease in CD4+ T cell count upon admission." (PMID 39650838, 2024). "Our finding that in vivo toll-like receptor (TLR) stimulation increases the number of ISG+ naïve T cells suggests that the pool of IFN-experienced naïve CD4+ T cells could be expanded by acute viral infection." (PMID 39321257, 2024). "Indeed, in addition to cell-free virus infection, macrophages can also become infected when engulfing infected CD4+ T cells as innate immune sentinels." (PMID 39339960, 2024). "However, CD4+ CTLs also play roles in defending the body from viral infection and tumors, and a recent study found that CD4+ CTLs killed senescent cells, which supports the protective effects of CD4+ CTLs in some contexts." (PMID 38499993, 2024). "The main factors contributing to the non-pathogenic nature of SIV infection in SMs are the absence of chronic immune activation, the observed low levels of microbial translocation, and a relative preservation of a specific CD4+ T-cell subset from direct virus infection (6, –, 15)." (PMID 39258922, 2024). "CD4 on TD CD4+ cells is commonly acknowledged as CD4 on Terminally Differentiated CD4+ T cells, recognized as a biologically significant subset of T cells playing pivotal roles in combating viral infections, suppressing tumor growth, and regulating immune responses." (PMID 39336774, 2024). "CD4+ T cells were isolated from peripheral blood mononuclear cells (PBMCs) using immunomagnetic purification and activated via CD3/CD28 co-stimulation to maximize their susceptibility to viral infection." (PMID 39205294, 2024). "Mathematical analysis of murine T cell responses to viral infection has shown that CD4+ T cells responding to an immunodominant epitope in lymphocytic choriomeningitis virus (LCMV) begin to divide between 48 and 72 h after stimulation and have a doubling time of 11 h in vivo." (PMID 38270554, 2024).
viral infection (continued). "TFH cells are described as a subpopulation of CD4+ T cells that play a critical role in the development of Ab-producing and memory B cells that might be important in immune response to viral infections." (PMID 39001456, 2024). "Upon virus infection, DOCK8 mutation CD4+ T cells have a Th2 effector fate." (PMID 39329018, 2024). "In addition to promoting the functions of B cells and CD8+ T cells, accumulating evidence suggests that CD4+ T cells also play a protective role through direct cytolytic activity during viral infections." (PMID 38770891, 2024). "Our study suggests that in addition to rare cases in which cross-reactive cells are established following viral infections, CD4+ TIA cells generated as part of the virus-specific memory response are recruited to the site of autoimmune inflammation where they are activated to produce IFN-γ." (PMID 38838013, 2024). "As JunB is a transcription factor, we hypothesized that the absence of JunB may alter the expression of host factors required for viral infection, such as CD4 or CXCR4." (PMID 38835488, 2024). "Specifically, while HIV’s entry receptor CD4 is indispensable for viral infection of CD4+ T-cells, its continued presence on the cell surface disrupts the processing of viral glycoproteins and reduces Envelope (Env) incorporation into virions, impeding their release and infectivity." (PMID 38883214, 2024). "Recent studies reported a critical role of CD4+ T cells in viral infection of the CNS." (PMID 39153993, 2024). "The ratio of CD4/CD8<1 has been connected with immune senescence or persistent viral infections." (PMID 39845961, 2024). "Cytotoxic mechanisms of CD4+ CTL killing not only differ between virus infections or types of malignancy, but may be influenced by immunological factors even within one model system." (PMID 37965314, 2023). "CD4+ T cells are essential players in immune defense and control of viral infections and cancer." (PMID 37965314, 2023). "For unknown reasons, control retro-virus infection also promoted overall cellular RORγt expression and decreased the frequency of CD4+NKp46+ ILC3s compared with mice under steady state." (PMID 36969227, 2023). "We also investigated whether IEC stimulation would increase R5 tropic virus infection of activated CD4 + T cells." (PMID 37202790, 2023). "Notably, the percentage of Th17 cells expressing α4β7 integrin was significantly higher compared to Th1 cells, and these data are supported by previous studies showing that α4β7hi CD4+ T cells harbor most Th17 cells during viral infection." (PMID 37143680, 2023). "Flow cytometry analyses of the HIV-1GKO viral infection of activated primary CD4+ T cells from two anonymous healthy donors demonstrated that depletion of PRMT2 leads to a marked increase in the proportion of productively infected cells and a concomitant significant decrease in latent infection." (PMID 37949879, 2023). "Other key elements for a decreased risk of virus infection are mucosal NKp44+ cells producing IL-17 that maintain tissue homeostasis and vaccine-induced gut-homing CD4+ T-cells expressing low or no CCR5." (PMID 38005994, 2023). "The CD4+ polypositive (or polyfunctional) T-cell response detected here is generally important for an effective viral vaccine and often correlates with better protection against viral diseases." (PMID 37435073, 2023). "However, many researchers have identified cytotoxic CD4+ T cells that display direct killing effects in autoimmune diseases, viral infections, and aging process." (PMID 37829505, 2023). "Altogether, our findings shed new light on hepatic CD4+ T cell profile that could contribute to liver injury following viral infection." (PMID 37656815, 2023). "CD4+ T cells play a significant role in the adaptive immune response to hepatic viral infections." (PMID 36992265, 2023).
viral infection (continued). "We speculate that the cellular immune response induced by epitope 264EPSPREP270, promoting CD8+ T cell metabolism but inhibiting CD4+ T cell metabolism, may contribute to the efficient clearance of viral infection." (PMID 37370477, 2023). "Besides the death of CD4+ cells caused directly by HIV-1, one of the factors of progressively diminishing the CD4+ pool is pyroptosis, which is triggered by abortive viral infection." (PMID 37376629, 2023). "This infection mode was more efficient than cell-free virus infection and dependent on CD4 expression on target macrophages as we observed a 75% inhibition in the infection index when macrophages were pre-treated with anti-CD4 antibodies (n > 270 nuclei/condition)." (PMID 36988579, 2023). "The down-regulation of CD4+ Tem cell number and activation suggests that these cells may be involved in viral infection." (PMID 37033979, 2023). "CD4 T cells express all three classes of caspases and the transcriptions of caspase 2 and 10 (initiator), caspase 1 (inflammatory), and caspase 3 and 7 (executioner) were upregulated during the viral infection." (PMID 36780482, 2023). "Therefore, unique long-term transcriptional profiles are induced in memory antigen-specific CD4+ T cells depending upon the context of initial antigen exposure, either mRNA vaccination or viral infection." (PMID 37790414, 2023). "Unlike CD4+ T cells, which have a clear mechanism of depletion via direct viral infection, the mechanism behind this tissue-dependent loss of CD8+ T cells during SIV infection is not well understood and warrants further investigation." (PMID 37039653, 2023). "In addition to cell-free virus infection, macrophages can be infected when engulfing infected CD4+ T cells." (PMID 37476291, 2023). "ISG+ CD4+ T cells have been previously found in the blood and kidneys of patients with lupus nephritis, and in mouse during chronic viral infections, allergic airway inflammation, and colonic infection." (PMID 37624388, 2023). "We investigated the role of immune activation and potentially compromised T-cell responses in the three different chronic viral infections by exploring conventional CD4+ and CD8+ T cells along with their counterpart follicular T helper cells (Tfh) and mucosal-associated invariant T cells (MAIT)." (PMID 37163092, 2023). "However, greater attention needs to be paid to PLWH with uncontrolled viral infection and/or low CD4+ T-cell counts and to the effects of aging and comorbidities." (PMID 37766251, 2023). "These cells are prominent in viral infections that target HLA class II-expressing cells such as Cytomegalovirus, Epstein Bar Virus, Dengue, and Human Immunodeficiency Virus, and which include antigen-presenting cells (DC, B cells) and CD4+ T cells." (PMID 38001069, 2023). "Similarly, exhaustion markers Lag3, Tigit, and Ctla4 were uniformly increased in all CD4+ T cell subsets responding to chronic viral infection." (PMID 36255051, 2022). "Thus, reversed function CD8/MHC-I helper and CD4/MHC-II cytotoxic T cells fail to provide protective immunity against viral infections." (PMID 35523960, 2022). "While CD4+ T cells initially differentiate towards a Th1 phenotype during Cl13 infection, they eventually transition and acquire a Tfh phenotype at late stages of chronic viral infection." (PMID 35774790, 2022). "Collectively, these data may serve as a useful resource to assess and compare the transcriptional landscape and differentiation trajectory of virus-specific CD4+ T cell clones during acute and chronic viral infection." (PMID 36255051, 2022). "The negative aspect of such immunomodulatory properties, which could be largely beneficial in many viral infections, could be the increase in the frequency of proliferating activated CD4+ T cells, ideal “prey” for HIV." (PMID 35185880, 2022).